CFP (complement factor properdin)
Description:
A positive regulator of the alternate pathway (AP) of complement. It binds to and stabilizes the C3- and C5-convertase enzyme complexes. Inhibits CFI-CFH mediated degradation of Complement C3 beta chain (C3b).
Synonyms: PFC; BFD; PFD; PROPERDIN
Tractability: Small molecule: a structure with a bound ligand is known. Antibody: UniProt places it where antibodies can reach, with high confidence; its Gene Ontology location is reachable by antibodies, with high confidence; UniProt predicts a signal peptide or a membrane-spanning region.
Gene: Protein-coding gene on chromosome X (47,621,537 to 47,630,305, reverse strand). Ensembl gene ENSG00000126759.
Subcellular location: Secreted
Subcellular location (Human Protein Atlas): Vesicles; Predicted to be secreted
Pathways (Reactome):
Immune System: Activation of C3 and C5; Alternative complement activation; Neutrophil degranulation; Regulation of Complement cascade
Disease: Defective B3GALTL causes PpS
Metabolism of proteins: O-glycosylation of TSR domain-containing proteins
Gene Ontology:
Molecular function: protein binding
Biological process: positive regulation of complement activation, alternative pathway; protein stabilization; complement activation; defense response to bacterium; immune response; positive regulation of immune response; positive regulation of opsonization; complement activation, alternative pathway
Cellular component: cytoplasmic side of Golgi membrane; extracellular region; endoplasmic reticulum lumen; specific granule lumen; tertiary granule lumen; secretory granule
Homologues: Orthologues: chimpanzee CFP (99% identical), macaque CFP (93% identical), rabbit CFP (78% identical), rat Cfp (78% identical), guinea pig CFP (75% identical), pig CFP (75% identical), mouse Cfp (75% identical), dog CFP (74% identical), tropical clawed frog cfp (44% identical), zebrafish cfp (39% identical), zebrafish si:ch73-237c6.1 (39% identical), Caenorhabditis elegans C36B7.5 (32% identical).
Diseases named in the same sentence as CFP in open-access papers:
CFP is named in the same sentence as 85 diseases in open-access papers, as found by Europe PMC text mining. Sharing a sentence is not in itself a finding about the gene and the disease. The quoted sentences say what the papers report.
breast carcinoma (8 papers, 2011 to 2023). "The expression of intracellular malondialdehyde (MDA) and carbonylation protein (CFP) gradually increased with longer treatment time of quercetin, revealing that quercetin inhibited breast cancer cell development by causing ferroptosis." (PMID 35898781, 2022). "Mono_CX3CR1 cells also highly expressed CFP, which has been reported to suppress breast cancer growth by inducing apoptosis." (PMID 36869384, 2023). "Since most breast cancer bone metastases generate osteolytic bone lesions, we expanded our analysis of the metastatic niche to include osteoblastic cells (CFP+ cells in Col2.3-CFP reporter mice backcrossed onto a BALB/c background)." (PMID 34836954, 2021). "Notably, CFP expression significantly impacted prognosis in 8 cancer types, namely, blood cancer, brain cancer, breast cancer, lung cancer, ovarian cancer and soft tissue cancer." (PMID 33976747, 2021). "While latest studies 12 have shown that CFP up-regulates TES mediated transcription factor DDIT3 to inhibit the growth of breast cancer cells, the relationship between CFP and other tumors has not been reported." (PMID 33976747, 2021). "Block and coworkers reported that complement factor properdin (CFP), known to be a secreted protein and a regulator of innate response functioning as a pattern recognition molecule, suppresses the growth of breast cancer cells by inducing ER stress rather than by eliciting immune responses." (PMID 33859174, 2021).
glioma (7 papers, 2012 to 2026). A benign or malignant brain and spinal cord tumor that arises from glial cells (astrocytes, oligodendrocytes, ependymal cells). "To characterize the potential effect of glioma released soluble factors on neuronal [Cl−]i, we used genetically encoded CFP/YFP-based ratiometric Cl-(apical) Sensor transiently expressed in cultured hippocampal neurons." (PMID 23189038, 2012). "In the present study, we characterized the effect of neuroactive aminoacids released by glioma cells on neuronal [Cl−]i, taking advantage of a genetically encoded CFP/YFP-based ratiometric Cl-Sensor, which was transiently expressed in cultured hippocampal neurons." (PMID 23189038, 2012). "The genetically engineered autophagy deficient mouse mIDH1 glioma model was developed using the Sleeping Beauty (SB) Transposon System through a combination of SB-transposase/LUC; NRAS/shP53/GFP; shATRX/GFP; IDH1R132H/Kat and shATG7/CFP plasmids." (PMID 40964044, 2025). "In order to assess whether substances released from glioma cells may alter neuronal chloride homeostasis, we used a CFP/YFP-based ratiometric Cl-Sensor expressed in primary hippocampal neuronal cultures." (PMID 23189038, 2012). "Taking advantage of a genetically encoded CFP/YFP-based ratiometric chloride sensor (Cl-Sensor), we investigated how neuronal [Cl−]i is dynamically regulated by diffusible factors released by cultured glioma cells." (PMID 23189038, 2012). "From these genes, 8 were identified as independent prognostic factors for glioma (FGFR1, FLT3, VTN, NR2C1, SEMA4G, CFP, S100P, CHGB)." (PMID 41596318, 2026). "Tumor growth, optical and biochemical assessment of the microenvironment can be conducted by implanting reporter gene expressing glioma cells (i.e. fluorescent protein expression such as GFP, RFP, CFP and others)." (PMID 26673818, 2016). "Furthermore, the roles of the IGRPS genes NR2C1, SEMA4G, CFP, and CHGB in gliomas and other cancers are uncharacterized." (PMID 41596318, 2026). "The role of other genes (NR2C1, SEMA4G, CFP, CHGB) included in IGRPS has not been elucidated in gliomas and other tumors." (PMID 36676646, 2022).
lung carcinoma (5 papers, 2021 to 2025). "In stomach and lung cancer, the expression level of CFP was lower than in normal tissues, and low expression level of CFP was associated with poor prognosis." (PMID 38683466, 2025). "Among them, CFP is a tumor prognostic marker associated with immune infiltration in gastric and lung cancer." (PMID 36052090, 2022). "Research has indicated that CFP may serve as an independent risk factor for the prognosis of lung cancer and could be involved in regulating relevant immune mechanisms in the tumor microenvironment." (PMID 38468345, 2024). "CFP plays a positive role in regulating the natural immune system in alternative pathways, and it is associated with immune infiltration in gastric cancer and lung cancer." (PMID 36741376, 2022). "In summary, the low expression of CFP is closely related to the prognosis of multiple tumors (especially lung cancer and gastric cancer), and is associated with increased infiltration of immune cells such as CD8+ T cells, CD4+ T cells, macrophages and neutrophils." (PMID 33976747, 2021). "Several studies reported the tumor suppressive effect of CFP on melanoma, breast, stomach and lung cancer." (PMID 38683466, 2025). "In summary, SMC6, CDC27, CDC7, RACGAP1, SMC4, NCF1,2,4, SELPLG and CFP are significantly associated with T2DM and lung cancer, making them potential target genes for disease prediction and treatment in the future." (PMID 38468345, 2024). "Studies on transgenic mice have shown that CFP can be used as a general serum biomarker for lung cancer." (PMID 33976747, 2021). "Therefore, CFP may be expected to be an independent risk factor for the prognosis of lung cancer and gastric cancer, and may be involved in the regulation of relevant immune mechanisms in the tumor microenvironment, which need to be further identified in more clinical trials and basic experiments." (PMID 33976747, 2021). "Our results suggested that CFP may also play an important role in the recruitment and regulation of immune infiltrating cells in gastric and lung cancers." (PMID 33976747, 2021).
hepatoma (4 papers, 2014 to 2022). "Our result also showed its mRNA expression had correlations with tumor immune cells, including M2 macrophages, which might indicate the possible mechanism of CFP in regulating tumor immune cells in hepatocellular carcinoma." (PMID 34813686, 2022).
melanoma (4 papers, 2022 to 2025). A malignant, usually aggressive tumor composed of atypical, neoplastic melanocytes. "We generated two melanoma cell lines, MeWo (NRASWT) and WM-1366 (NRASQ61L), and one lung adenocarcinoma line, NCI-H1299 (NRASQ61K), that stably express CFP-FLAG-tagged Mb24 upon DOX treatment." (PMID 39379700, 2024).
diabetes (3 papers, 2017 to 2025). "Moreover, glucose intolerance and insulin resistance caused by diabetes were ameliorated by CFP and liraglutide as assessed by OGTT, ITT, and HOMA-IR index, and the effect tended to be stronger in liraglutide-treated group." (PMID 35958251, 2022). "Among the top 40 abundant bacterial taxa, CFP treatment resulted in clear enrichment of Dubosiella, Parasutterella, Ruminococcaceae, Muribaculum, Allobaculum, and Bifidobacterium, and mostly reversed the bacterial change caused by diabetes." (PMID 35958251, 2022). "In contrast, the abundance of Lachnospiraceae UCG 001 and UCG 002, Oscillospiraceae UCG 002, and Romboutsia increased in diabetes and was reduced by CFP treatment." (PMID 35958251, 2022). "There were a total of 33 functions that were significantly altered by diabetes or high-dose CFP treatment." (PMID 35958251, 2022). "Further studies are required identify the specific strain of bacteria that responsible for the effect of CFP in diabetes." (PMID 35958251, 2022). "Importantly, no adverse effect of CFP was found in our study, and CFP exerted a wider arrange of protection against diabetes than liraglutide." (PMID 35958251, 2022). "Importantly, unlike the adverse effect caused by liraglutide, such as appetite inhibition, no adverse effect of CFP was found in our study, and CFP exerted a wider arrange of protection against diabetes than liraglutide." (PMID 35958251, 2022). "Additionally, diabetes and HFD-induced hyperlipidemia, including elevated plasma TG, TC, and NEFA levels, was significantly improved by CFP treatment, but not in liraglutide-treated group." (PMID 35958251, 2022).
Granuloma (3 papers, 2011 to 2023). A compact, organized collection of mature mononuclear phagocytes, which may be but is not necessarily accompanied by accessory features such as necrosis. "CFP+ cells wereabundant in the lung parenchyma, and were concentrated in granulomas." (PMID 21637811, 2011). "Circulating CFP-10pep levels measured in a non-human primate model of tuberculosis distinguished disease from asymptomatic infection and tended to correspond with Mtb granuloma size, suggesting that it could also serve as a surrogate marker for Mtb burden and possibly treatment response." (PMID 35401822, 2022).
babesiosis (2 papers, 2023 to 2025). Babesiosis refers to a condition caused by microscopic parasites that infect the red blood cells. "Other identified proteins that differentiated uncomplicated from complicated babesiosis were various complement cascade components (CFI, CFP, C2, SERPING1, C8G), extracellular matrix components (TGFBI), acute phase proteins (ORM1, ITIH2, ITIH4, FGA, TF, RBP4) and lipoproteins (apoE)." (PMID 37353646, 2023).
colon carcinoma (2 papers, 2021 to 2022). "We speculated that CFP and CD55 might be involved in the immune infiltration of tumor cells in colon cancer." (PMID 36741376, 2022).
COVID-19 (2 papers, 2023). A disease caused by infection with severe acute respiratory syndrome coronavirus 2. "However, contrary to our results, they indicate that numerous human milk proteins involved in the immune response were downregulated in response to COVID-19, like markers for neutrophil degranulation (CD44 and complement factor properdin (CFP)) and leukocyte migration." (PMID 37628421, 2023).
gastric cancer (2 papers, 2021 to 2022). A primary or metastatic malignant neoplasm involving the stomach. "In particular, of the different stages of gastric cancer, low expression of CFP was associated with poor prognosis at stage 3, T3, N2 and N3." (PMID 33976747, 2021). "Besides, in stage 3, stage T3, stage N2 and N3, low expression of CFP was associated with worse survival in gastric cancer (P < 0.05)." (PMID 33976747, 2021). "In order to explore the relationship between CFP and gastric cancer, and its possible mechanism in gastric cancer, we used the Kaplan-Meier plotter database to analyze the relationship between CFP expression and clinical characteristics of gastric cancer patients." (PMID 33976747, 2021).
influenza (2 papers, 2018 to 2022). An acute viral infection of the respiratory tract, occurring in isolated cases, in epidemics, or in pandemics; it is caused by serologically different strains of viruses (influenzaviruses) designated A, B, and C, has a 3-day incubation period, and usually lasts for 3 to 10 days. "Histological analysis of lung tissue sections revealed that influenza infection-mediated lung injury, which was associated with immune cell infiltration into the lung and alveolar destruction, became more severe in mice receiving cFP at 7 days post-infection (dpi)." (PMID 29686409, 2018). "To test this, we generated a CFP-expressing influenza strain, leading to the labeling of infected cells with the fluorescent CFP protein (CFP-S-Flu)." (PMID 35349789, 2022).
leukemia (2 papers, 2018 to 2021). A malignant (clonal) hematologic disorder, involving hematopoietic stem cells and characterized by the presence of primitive or atypical myeloid or lymphoid cells in the bone marrow and the blood. "IVM of chimeras containing CFP+ osteoblastic cells, mTomato+ healthy hematopoietic cells, and YFP+GFP+ leukemia revealed that AML cells, as they remodel stroma and vessels locally, also outcompete healthy hematopoietic cells and eliminate osteoblastic cells." (PMID 29276143, 2018).
lung adenocarcinoma (2 papers, 2021 to 2024). A carcinoma that arises from the lung and is characterized by the presence of malignant glandular epithelial cells. "Finally, we evaluated the correlations between CFP and cancer immune infiltrates particularly in stomach adenocarcinoma (STAD) and lung adenocarcinoma (LUAD) by using GEPIA and TIMER databases." (PMID 33976747, 2021).
Obesity (2 papers, 2017 to 2023). Accumulation of substantial excess body fat. "Consistent with a role for obesity in promoting PDA growth, Obese-CFP tumors grew significantly larger (1.5-fold, P = 0.002, t-test) than Lean-CFP." (PMID 28808255, 2017).
viral infection (2 papers, 2013 to 2018). "Here the authors show the quorum sensing molecule cFP from Vibrio vulnificus inhibits the RIG-I mediated antiviral interferon response and enhances susceptibility to viral infection." (PMID 29686409, 2018).
age (1 paper, 2011). A temporal measurement of the time period elapsed since an identifiable point in the life cycle of an organism. "Secondly, we tested a yeast model for age-associated neurodegenerative disorders in which inducible CFP is fused to the first exon of huntingtin with toxic (Htt103Q) or non-toxic (Htt25Q) glutamine expansions." (PMID 21931558, 2011).
allergic rhinitis (1 paper, 2020). Inflammation of the nasal mucous membranes caused by an IgE-mediated response to external allergens. "C5aR1 and complement factor P (CFP) also known as Properdin, and circadian associated genes were also shown to exacerbate IL-5 and IL-13, the type 2 inflammatory cytokines and inflammasome pathway activation involving eosinophils in allergic rhinitis patients." (PMID 32923410, 2020).
Allergy (1 paper, 2024). An allergy is an immune response or reaction to substances that are usually not harmful. "The specific SNPs of allergy and non-allergic groups were mainly in trafficking protein particle complex subunit 2 (TRAPPC2), Pirin (PIR), complement factor properdin (CFP), and sosondowah ankyrin repeat domain family member D (SOWAHD), however only TRAPPC2 and PIR were non-synonymous mutations." (PMID 39881721, 2024).
Alzheimer disease (1 paper, 2017). A progressive, neurodegenerative disease characterized by loss of function and death of nerve cells in several areas of the brain leading to loss of cognitive function such as memory and language. "However, our results do not automatically imply, that CFP is not involved in degeneration, as we know from other studies that CFP deposition was positive in patient eyes with AMD and was associated with drusen-like deposition in Alzheimer’s disease." (PMID 28676742, 2017).
atherosclerosis (1 paper, 2025). A disease characterized by the build-up of fatty material and calcium deposition in the arterial wall resulting in partial or complete occlusion of the arterial lumen. "The probucol-loaded CFP nanoassembly exhibited superior ROS-scavenging and anti-inflammatory effects compared to both the CF nanozyme and probucol, attributed to the synergy of the nanozyme and the drug, thus facilitating a highly efficient treatment of atherosclerosis." (PMID 40271043, 2025).
bacteremia (1 paper, 2022). "This might be a potential bias between the different dosages received by the CFP–SUL groups regarding mortality in bacteremia caused by MDROs." (PMID 35453212, 2022). "In the CFP–SUL 1 g/1 g group, only one patient had bacteremia due to Acinetobacter spp." (PMID 35453212, 2022). "As for bacteremia caused by MDRO, the mortality rate, although not significantly different, seemed to be higher in the CFP–SUL 2 g/2 g group." (PMID 35453212, 2022).
C3 glomerulonephritis (1 paper, 2019). Glomerulonephritis characterized by C3 accumulation with little or absent deposition of immunoglobulin, in the absence of ultrastructural electron-dense transformation seen in dense deposit disease. "For example, double knockout of complement factor H (CFH) and factor P (CFP) unexpectedly converts mild C3 glomerulonephritis to lethal C3 glomerulonephritis in mice." (PMID 31604923, 2019).
developmental delay (1 paper, 2017). "The increased body weight and developmental delay observed in PTTH-GAL4/UAS-TeTxLC::CFP line were reversed by 20E-feeding, suggesting that the reduction of 20E titer by suppression of PTTH neural transmission is the cause of these phenotypes." (PMID 28924263, 2017).
endotoxemia (1 paper, 2022). "We found that CFP protected gut barrier function by alleviating endotoxemia and enhancing tight junction and mucin secretion, and these effects were stronger in high-dose CFP treated mice than those of liraglutide-treated ones." (PMID 35958251, 2022).
Fanconi anemia (1 paper, 2022). Fanconi anemia (FA) is a hereditary DNA repair disorder characterized by progressive pancytopenia with bone marrow failure, variable congenital malformations and predisposition to develop hematological or solid tumors. "We found that the lower mRNA expressions of C1R, C6, C7, CFP, and CFHR3 were correlated with pathways like Fanconi anemia pathway, cell cycle, MicroRNAs in cancers, and so on." (PMID 34813686, 2022).
kidney damage (1 paper, 2022). "Therefore, the protection against kidney damage by CFP might be partly regulated by microbiota-mediated tyrosine metabolism." (PMID 35958251, 2022).
liver disease (1 paper, 2018). "Regarding the severe liver dysfunction observed in chronic HCV patients co-infected with V. vulnificus, several possible interpretations other than cFP-mediated inhibition of RIG-I activation may also explain such fulminant liver disease with high mortality." (PMID 29686409, 2018).
lung squamous cell carcinoma (1 paper, 2021). "However, CFP expression exerted less influence on ovarian cancer besides PFS, and showed a better relation with FP and PPS in lung squamous cell carcinoma." (PMID 33976747, 2021).